IL6 (interleukin 6)
Diseases named in the same sentence as IL6 in open-access papers (continued):
Sharing a sentence is not in itself a finding about the gene and the disease.
systemic inflammatory response syndrome (continued). "On the other hand, excessive IL-6 production has been linked to the development of acute and life-threatening complications such as systemic inflammatory response syndrome (SIRS) and cytokine-release syndrome." (PMID 40191199, 2025). "Follow-up of survivors at six and twelve months post-discharge, including evaluation of cognitive function, quality of life, and functional status, could determine whether admission biomarker profiles, particularly IL-6 levels, predict the risk of developing post-sepsis syndrome." (PMID 40959673, 2025). "Notably, the data regarding IL-6 suggest potential benefits of using the larger Impella 5.5, which may be associated with reduced systemic inflammatory response syndrome and possibly better hemodynamic support." (PMID 39768841, 2024). "IL-6 is an important cytokine that is rapidly induced over the course of infection and could be used as a diagnostic aid to confirm infection in patients with systemic inflammatory response syndrome." (PMID 35242747, 2022). "Therefore, the elevated cytokines (interleukin-6, -8, -10), caused by systemic inflammatory response syndrome triggered by influenza virus infection, have been hypothesized to play an important role in the pathogenesis of neurological complications." (PMID 34246228, 2021). "Previous studies have showed that CRP and IL-6 level was associated with the development of systemic inflammatory response syndrome (SIRS)." (PMID 33478333, 2021). "Experimental evidence has identified IL-6 as a key regulator that promotes erythropoietin synthesis during systemic inflammatory response syndrome following septic shock in pediatric populations." (PMID 40895306, 2025). "Massive release of IL-2, IL-6, and TNF-α underlies the systemic inflammatory response syndrome (SIRS)." (PMID 41010851, 2025). "Inflammatory factors such as TNF, IL-1, and IL-6 contribute to a cytokine storm, resulting in tissue damage, severe systemic inflammatory response syndrome (SIRS), and multiorgan failure." (PMID 38957461, 2024). "After activation, large amounts of TNF-α and IL-6 are released by monocytes, which results in systemic inflammatory response syndrome." (PMID 39200283, 2024). "IL-6 is a typical cytokine which helps to maintain homeostasis, but dysregulated excessive and persistent synthesis of IL-6 can have pathological effects on the acute systemic inflammatory response syndrome." (PMID 38672400, 2024). "Progesterone improves sepsis syndrome by reducing inflammatory cytokines, IL-6 and TNF-α and by restoring the antioxidant defense system." (PMID 37077915, 2023). "Since gp130 is a widely spread transmembrane protein, IL6 extends its sphere across the organism, contributing to an overwhelming immune response, which can result in “systemic inflammatory response syndrome” (SIRS), contributing to the development of MOF." (PMID 36151360, 2023). "A previous study found that continuous hemofiltration increases IL-6 plasma clearance but cannot change its plasma concentration effectively in systemic inflammatory response syndrome (SIRS)." (PMID 36383295, 2023). "Vitamin A has been shown to have a dose-dependent antagonistic effect on IL-6, a protein that plays a key role in development of the systemic inflammatory response syndrome." (PMID 36803946, 2022). "Via immune activation, DAMPs trigger a systemic inflammatory response syndrome (SIRS) that is characterised in part by elevated circulating concentrations of a range of pro-inflammatory cytokines (Interleukin IL6, Tumor Necrosis Factor α)." (PMID 36471343, 2022). "Systemic inflammatory response syndrome plus CRP was more accurate than systemic inflammatory response syndrome plus IL-6 (AUC 0.79 vs. 0.72) for the prediction of SAP." (PMID 36467730, 2022). "Gypsum fibrosum reduced the serum levels of TNF-α and IL-6, and IL-1β, TNF-α, and IL-6 in lung tissues in mice with systemic inflammatory response syndrome induced by lipopolysaccharide." (PMID 33693014, 2021).
systemic inflammatory response syndrome (continued). "Shenfu injection alleviated lung injury in a rat systemic inflammatory response syndrome model by inhibiting NF-B activation and decreasing the plasma level of IL-6 and TNF-α." (PMID 34393772, 2021). "It has been postulated that IL-1 released from monocytes and macrophages activates endothelial expression of NO and IL-6, which in turn induce an acute phase response complicated by the systemic inflammatory response syndrome (SIRS)." (PMID 34360549, 2021). "The current view is that influenza virus infection triggers a systemic inflammatory response syndrome, in particular, elevated cytokines (interleukin-6, -8, -10) are involved." (PMID 34246228, 2021). "Problems arise when this unbalanced inflammatory response escalates and releases an excess of pro-inflammatory mediators such as IL-1, IL-6, IL-8, and TNFα, culminating in systemic inflammatory response syndrome (SIRS)." (PMID 32019485, 2020). "It was reported that VA has a dose-dependent antagonistic effect on IL-6, which exerts an important role in the process of systemic inflammatory response syndrome." (PMID 31370866, 2019). "In the literature, elevated IL-6 UCB levels at birth were reportedly associated with an increased risk of neonatal morbidity and mortality, including neonatal sepsis, systemic inflammatory response syndrome, PVL, and NEC." (PMID 30327582, 2018). "In this experimental model, we have shown previously that plasma levels of IL-6, a common marker of the systemic inflammatory response syndrome, peak at 6 h." (PMID 29234326, 2017). "IL6, MCP-1, and TNFα have been defined by one author as being involved in “systemic inflammatory response syndrome”, while MIP1 and TNFα are more specifically associated with “neutophilic inflammation”." (PMID 24586996, 2014). "Numerous studies made on patients or animals with systemic inflammatory response syndrome of infectious origin, sustain the predictive potential of IL–6 and TNF alpha, which have the capacity to predict the evolution towards septic complications." (PMID 21776298, 2011). "Effects of CO administration on cytokine (TNF-alpha, IL-6, IL-1beta and IL-10) release were investigated in a porcine model in which a systemic inflammatory response syndrome was induced by endotoxin infusion." (PMID 18687112, 2008). "It is unlikely that the systemic inflammatory response syndrome response elicited by the extracorporal bypass has a major role because IL-6 and IL-10 production in the mediastinal cavity exceeded systemic production 1,000-fold and 10-fold, respectively." (PMID 16356228, 2005). "In the early stages of sepsis, a subset of activated macrophages, characterized by their expression of proinflammatory markers such as TNF-α, IL-1β, and IL-6, plays a pivotal role in activating the coagulation and complement systems, thereby inducing systemic inflammatory response syndrome (SIRS)." (PMID 41169382, 2025). "Furthermore, deferoxamine has been found to reduce the release of inflammatory mediators including IL-6 and TNF-α, thereby mitigating tissue damage caused by systemic inflammatory response syndrome (SIRS)." (PMID 41401162, 2025). "However, the persistent production of IL-6 exerts detrimental effects on acute systemic inflammatory response syndrome and chronic immune-mediated disorders." (PMID 39858184, 2025). "IL-6 is a characteristic manifestation of the systemic inflammatory response syndrome." (PMID 40386212, 2025). "Trauma and surgical stress responses are associated with significantly elevated numbers of suppressive CD14 + HLA-DRlow/-monocytes and CD16BRIGHT CD62LDIM neutrophils, leading to activation of inflammatory factors such as interleukin 6 and inducing a systemic inflammatory response syndrome." (PMID 37140597, 2023). "Interestingly, immature granulocytes are associated with early-stage infections and have been shown to be better markers than CRP and IL-6 for systemic inflammatory response syndrome." (PMID 37147304, 2023).
systemic inflammatory response syndrome (continued). "Similarly, it is shown that lower IL-6 and IL-1β were conducive to protect against lethality in sepsis syndrome via the JNK signaling pathway and the transcription factor AP-1." (PMID 32802115, 2020). "Impaired IL6 function causes enhanced susceptibility of mice to infection of Listeria monocytogenes, but excessive and sustained production of IL6 can be life-threatening, including systemic inflammatory response syndrome (SIRS) and chronic inflammatory diseases." (PMID 32851030, 2020). "In this regard, Tat-Tg mice were more susceptible to the systemic inflammatory response syndrome caused by the intra-peritoneal injection of LPS, based on the evidence of increased lethality and expression levels of TNF-α, IL-1α, IL-6 and CXCL10 in the peritoneal lavages of surviving animals." (PMID 26343909, 2015). "In addition, continuous hemofiltration was also ineffective in lowering circulating IL-6 levels in patients with systemic inflammatory response syndrome." (PMID 24755610, 2014). "Central to this process is the cytokine storm, driven by uncontrolled release of TNF-α, IL-1β, and IL-6, which exacerbates systemic inflammatory response syndrome (SIRS) and tissue injury." (PMID 41262247, 2025). "IL-6 levels rise rapidly after injury and correlate strongly with the severity of systemic inflammatory response syndrome (SIRS), myocardial dysfunction, and multi-organ failure." (PMID 40710793, 2025). "Furthermore, serum acetylcholine (ACh) reduces the production of inflammatory cytokines (TNF-α, IL-1β, IL-6, and IL-18) through the alpha 7 nicotinic acetylcholine receptor subunit (α7nAChR) hereby preventing systemic inflammatory response syndrome (SIRS) development." (PMID 40299464, 2025). "A full-flow microaxial pump (Impella 5.5) seems advantageous regarding systemic inflammatory response syndrome (SIRS) and acute hemolysis, indicated by lower IL-6 and higher haptoglobin levels, compared with smaller Impella devices." (PMID 39768841, 2024). "In the context of systemic inflammatory response syndrome (SIRS) and sepsis, enterocytes exhibit elevated secretion of IL-6, which is also presented by the intestinal endothelium, macrophages, and helper T cells." (PMID 39767803, 2024). "IL-6 not only activates neutrophils but also delays phagocytosis of senescent and dysfunctional neutrophils, thereby exacerbating the production of post-traumatic inflammatory mediators and promoting the onset of post-traumatic systemic inflammatory response syndrome." (PMID 39371337, 2024). "Especially, the high level of IL6 indicated the development of systemic inflammatory response syndrome (SIRS)." (PMID 36817796, 2023). "Once ALF progresses, inflammatory cytokines such as TNF-α and IL-6 are released into the bloodstream and activate inflammatory monocytes, leading to systemic inflammatory response syndrome (SIRS)." (PMID 37941897, 2023). "In the early stage of ALI, local neutrophils and macrophages infiltrate in the lung tissues and secrete various cytokines like TNF-α, IL-6, and IL-1β, which can further activate leukocytes and cause systemic inflammatory response syndrome (SIRS) if inflammation is not controlled." (PMID 35264058, 2022). "This subsequently sparks a large-scale systemic inflammatory response, often termed the systemic inflammatory response syndrome (SIRS), resulting in an increase of inflammatory cells and mediators (ex: T cells, IL-1, IL-6, TNFa)." (PMID 35874126, 2022). "Continuous infusion of ghrelin after esophagectomy reduces the duration of systemic inflammatory response syndrome (SIRS) by lowering C-reactive protein and IL-6." (PMID 35454106, 2022). "Following brain injury, several cytokines, including TNF-α, IL-6, and CD11d, are released into circulation as part of the systemic inflammatory response syndrome (SIRS)." (PMID 36043003, 2022).
systemic inflammatory response syndrome (continued). "Extracorporeal circulation contributes to AKI because of red blood cell hemolysis and the systemic inflammatory response syndrome (SIRS), that induces the increase in blood levels of mediators, such as IL-6, IL-8 and TNF-α." (PMID 34019579, 2021). "In the same way, IL-6 induces hepatic synthesis of acute phase proteins, and IL-1β and TNF-α participate in systemic inflammatory response syndrome and multiple organ failure." (PMID 40868835, 2025). "The primary mechanism of organ failure in SAP patients is systemic inflammatory response syndrome (SIRS), which leads to the accumulation of inflammatory mediators and metabolic toxins (e.g., IL-6 and C-reactive protein)." (PMID 40324238, 2025). "During conditions such as systemic inflammatory response syndrome (SIRS) and sepsis, enterocytes increase IL-6 secretion." (PMID 40724804, 2025). "Amelioration of systemic inflammatory response syndrome (SIRS) induced by OMV was observed through the administration of salbutamol and nortriptyline, which exhibited inhibitory effects on the release of IL-6 and tumor TNF from macrophages." (PMID 38420121, 2024). "In general, IL‐6 and TNF‐α are involved in the pathogenesis of systemic inflammatory response syndrome." (PMID 38124471, 2024). "The post-injury systemic inflammatory response syndrome (SIRS) may worsen due to the presence of inflammatory cytokines such as IL-6." (PMID 38956520, 2024). "Systemic inflammatory response syndrome (SIRS) is the result of an unbalanced inflammatory response that escalates and releases an excessive amount of inflammatory mediators, such as IL-1, IL-6, IL-8, and TNF." (PMID 36900099, 2023). "Meanwhile, CRP 25.99 mg/L, IL-6 > 5000.0 ng/L, and PCT 11.72 ng/ml, indicating the diagnosis of systemic inflammatory response syndrome (SIRS)." (PMID 36817796, 2023). "Further, in a Phase 2 open-label study in patients with acute pancreatitis with accompanying systemic inflammatory response syndrome (SIRS) and hypoxemia, it was noted that Auxora rapidly lowered IL-6 levels in those patients presenting with levels > 150 pg/mL." (PMID 35395943, 2022). "This ongoing inflammation releases pro-inflammatory cytokines interleukin (IL)-1, IL-6, and IL-8 and systemic mediators such as tumor necrosis factor-alpha (TNF-α) leading to systemic inflammatory response syndrome (SIRS)." (PMID 35449658, 2022). "The release of such inflammatory mediators such as IL-6 and tumor necrosis factor-alpha (TNF-alpha) leads to systemic inflammatory response syndrome." (PMID 35740350, 2022). "Proinflammatory cytokines, including IL-1β, IL-6, and HMGB1, mediate the inflammatory response of immune cells and promote systemic inflammatory response syndrome." (PMID 34790828, 2021). "The pro-thrombotic state is usually promoted by a high expression of IL-6, followed by ICAM-1 (Intercellular Adhesion Molecule 1) expression and endotheliites, generating a systemic inflammatory response syndrome." (PMID 33806100, 2021). "This connection is notable enough that IL-6 was initially used to define an entity termed fetal inflammatory response syndrome (FIRS), the fetal corollary to adult systemic inflammatory response syndrome (SIRS)." (PMID 32636848, 2020). "PCT, IL-6 and CRP cannot be utilized to differentiate Systemic Inflammatory Response Syndrome (SIRS) from infection, in patients who receive ATG or similar within up to three days after the application of the drug." (PMID 26543528, 2015). "Sequential Organ Failure Assessment (SOFA) score; systemic inflammatory response syndrome score; white blood cell count; and serum C reactive protein, procalcitonin (PCT), interleukin-6 (IL-6), lactate, albumin, and hemoglobin levels were recorded." (PMID 25460569, 2014). "Serum molecules like IL-1β, IL-6, TNF-α, ICAM-1, and E-selectin were involved in the pathophysiology of systemic inflammatory response syndromes." (PMID 24693284, 2014).
systemic inflammatory response syndrome (continued). "Although the adverse events of the cytokines (IL6, IFN-γ, TNF-α) occurred, the concentrations of the released cytokines were much lower than adoptive T therapy method and the systemic inflammatory response syndrome was reversible." (PMID 24086580, 2013). "Systemic inflammatory response syndrome is characterized by increased serum levels of TNF-α, ICAM-1, E-selectin, IL-1β, and IL-6." (PMID 24369441, 2013). "A randomized crossover study of 13 patients with AKI and the systemic inflammatory response syndrome found that CVVH for 24 hrs reduced plasma concentrations of TNFα and cleared more IL-6, compared to CVVHD." (PMID 23095370, 2012). "Physiologically, IL-6 can cause the activation of leukocytes and promotion of TNF-α release and accounts for fever and leukocytosis present in systemic inflammatory response syndrome (SIRS)." (PMID 22655044, 2012). "Discussion: The study of IL–1 beta, IL–6 and TNF alpha blood dynamics, offers valuable information about the severity of a systemic inflammatory response syndrome in peritonitis." (PMID 21776298, 2011). "One study found that only patients with systemic inflammation signs of systemic inflammatory response syndrome, and/or elevated levels of proinflammatory cytokines (tumor necrosis factor-a [TNF-a], interleukin-6 [IL-6]) developed HE in the presence of hyperammonemia." (PMID 37892060, 2023). "An inflammatory response characterized by elevated interleukin 6 (IL-6, 13.91 pg/mL), interferon-γ (IFN-γ, 45.55 pg/mL), IL-12P70 (5.63 pg/mL) was observed on day 8 after disease, indicating the development of systemic inflammatory response syndrome." (PMID 36357398, 2022). "Specifically, we found of significant elevation of the inflammatory cytokines IL-1β, TNF-α, IL-6, and CXCL1 in the peripheral circulation at P10, around human term age equivalent, in POE rats suggesting a systemic inflammatory response syndrome (SIRS)-like response." (PMID 37396628, 2022). "High concentrations of pro-inflammatory cytokines (predominantly IL-6) and lack of compensatory expression of anti-inflammatory cytokines may cause systemic inflammatory response syndrome (SIRS)." (PMID 34635066, 2021). "Even though IL-6 is an important factor for the induction of the systemic inflammatory response syndrome, it is not the sole one, but a cascade of inflammatory mediators." (PMID 32722596, 2020). "Further it was noted that IL-10 encoding SNP genes were found responsible for exacerbating systemic inflammatory response syndrome (SIRS) score during CAP infection but not the TNF-α and IL-6 cytokines." (PMID 33634060, 2020). "IL-6 may play a pivotal role in the pathogenesis of PIS, whichrepresents a systemic inflammatory response syndrome initially observed followingendovascular aortic repair of infrarenal abdominal aortic aneurysms." (PMID 31112020, 2019). "Cytokines (TNF-α and IL-6) are important components of the immune system because they act as messengers between cells, but they are also involved in many pathological aspects of the cascade leading to systemic inflammatory response syndrome (SIRS) and ultimately MODS." (PMID 28198368, 2017). "On contrary, circulating IL-6 and IL-10 is assessed as prognostic markers of severity of the disease in the elderly, and these inflammatory indices categorize patients into systemic inflammatory response syndrome (SIRS) and non-SIRS groups." (PMID 24049644, 2012). "KICS, a more recently recognized condition, is characterized by systemic inflammatory response syndrome (SIRS) with high levels of HHV-8 viremia and elevated interleukins (IL-6 and IL-10)." (PMID 40407649, 2025). "In trauma, systemic inflammatory response syndrome (SIRS), or severe burns, insulin reduces pro-inflammatory mediators (TNF-a, IL-6, CRP, IFN-y, IL-18)." (PMID 39838305, 2025).